NF2 (NF2, moesin-ezrin-radixin like (MERLIN) tumor suppressor)
Diseases named in the same sentence as NF2 in open-access papers (continued):
Sharing a sentence is not in itself a finding about the gene and the disease.
meningioma (continued). "Thus, there is no available chemotherapeutic treatment for these tumors besides surgery, a situation especially traumatic for patients suffering bilateral vestibular schwannomas and several meningiomas such as those affected by NF2." (PMID 25333347, 2014). "By contrast, a similar localization pattern was observed for the 6 NF2-mutated tumors and the other 14 non-mutated meningiomas." (PMID 24171707, 2013). "Although monosomy 22/del(22q) is present in half of all meningiomas, and meningiomas frequently carry NF2 mutations, no study has been reported so far in which both alterations are simultaneously assessed and correlated with the features of the disease." (PMID 24171707, 2013). "In the present study, we demonstrate the existence of a close association between NF2 mutation and monosomy 22 but not del(22q), in sporadic meningiomas." (PMID 24171707, 2013). "Our results show a significant frequency of NF2 mutations (6/20 patients, 30%), most of which (5/6) had not been previously reported in sporadic meningiomas." (PMID 24171707, 2013). "Disruption of the Neurofibromatosis type 2 (NF2) gene, on human chromosome 22, leads to the development of the autosomal dominant disorder Neurofibromatosis type 2, characterized by the development of schwannomas, meningiomas, and ependymomas." (PMID 23308224, 2013). "Moreover, patients with NF2 develop other tumors as well, such as meningiomas, ependymomas and gliomas." (PMID 23354516, 2013). "Overall, six distinct NF2 mutations were found (6/20 cases; 30%) five of which had not been previously reported in sporadic meningiomas." (PMID 24171707, 2013). "In 1–8% of patients, meningiomas present as multiple tumors either due to a predisposing NF2 mutation or due to noncontiguous spread of a single sporadic tumor." (PMID 19589153, 2009). "Previous mutational analysis identified somatic NF2 mutations in the sporadic multiple meningiomas but not in the familial cases." (PMID 19589153, 2009). "Co-occurrence of multiple meningiomas in individuals who do not have germline NF2 mutation occurs far less frequently than do solitary meningiomas." (PMID 19589153, 2009). "Meningiomas may occur either as familial tumors in two distinct disorders, familial multiple meningioma and neurofibromatosis 2 (NF2), or sporadically, as either single or multiple tumors in individuals with no family history." (PMID 19589153, 2009). "Altogether, these data indicate that in the mouse homozygous inactivation of p16ink4 tumor suppressor gene, with retained p19Arf function, synergizes with Nf2 loss in meningioma initiation, but not in meningioma progression." (PMID 17924978, 2008). "The meningioma had no mutation in the NF2 gene and displayed a complex karyotype, as evidenced by single-nucleotide polymorphism analysis, including extensive losses on chromosome arm 1p, but no loss of chromosome 22 (data not shown)." (PMID 18087273, 2008). "Although these mice do not spontaneously develop schwannomas, meningiomas, or mesotheliomas, mouse models for each have been developed through the use of conditional mutant Nf2 alleles." (PMID 17971776, 2008). "Sequencing of the 17 exons of NF2 in constitutional, meningioma, and myoepithelioma DNA of patient III-1 revealed no mutations." (PMID 18087273, 2008). "There are reports of the loss of chromosome 22 as the primary consistent aberration in meningiomas, in the absence of mutations in the NF2 gene." (PMID 17222329, 2007). "Additionally, alterations in other genes such as SMO, AKT1, TRAF7, and KLF4 have been identified, particularly in non-NF2 mutant meningiomas, indicating a heterogeneous molecular landscape that may influence both prognosis and treatment response." (PMID 41007735, 2025).
meningioma (continued). "Additionally, 4/6 (67%) of the sporadic meningioma were non-skull base (n = 3 convexity, and n = 1 parasagittal) and therefore were more likely to harbour NF2 pathogenic variants than the two skull-base meningioma (n = 2 middle or posterior cranial fossa)." (PMID 41437121, 2025). "However, a further 2% of schwannoma patients and 4% of meningioma patients had multiple tumours without fulfilling diagnostic criteria for NF2-SWN." (PMID 41160189, 2025). "An important prognostic factor is the loss of chromosomal arm 1p in meningiomas, as ‘oncogenic phylogeny models propose 1p loss as the first CNV after monosomy 22q in NF2‐mutant, high‐grade meningiomas, with rare cases showing 1p loss in the absence of 22q loss (...)’." (PMID 40356449, 2025). "Interestingly, the majority of sporadic VS harbour NF2 pathogenic variants which are also common in non-skull base sporadic meningioma." (PMID 41437121, 2025). "A better understanding of the molecular drivers of tumor progression and recurrence, such as the roles of NF2, SMO, AKT1, TRAF7, and KLF4 mutations, will facilitate the development of targeted therapies, potentially improving outcomes for patients with atypical and anaplastic meningiomas." (PMID 41007735, 2025). "Given that as many of 60% of people with a clinical presentation consistent with NF2-SWN may have mosaic disease, clinicians should be aware of the need to test blood and ideally ≥ 2 potentially associated tumours (i.e. schwannoma, meningioma, ependymoma) from distinct regions of the nervous system." (PMID 41160189, 2025). "First, it is well characterized in the literature that hypermitotic and immune-enriched meningiomas have highly unfavorable clinical outcomes, substantial cell proliferation, and carry nearly total resistance to cytotoxic therapies due to misactivation of FOXM1 and loss of Merlin/NF2." (PMID 40867323, 2025). "The latest update from consortium to inform molecular and practical approaches to CNS tumor taxonomy-not official WHO (cIMPACT-NOW) suggest that meningiomas with 1p deletion and concurrent NF2 mutations and/or 22q monosomy should be graded at minimum as CNS WHO grade 2 tumors." (PMID 40447281, 2025). "Unlike meningiomas, where NF2 mutations are common, such mutations are very rare in GBM (< 2%)." (PMID 41487565, 2025). "Young patients with NF2 (<33.7 years) had a more severe clinical phenotype compared to older patients with NF2 (>33.7 years) with respect to their vital status (deceased, % = 38 vs. 0), the presence of meningiomas (patients, % = 100 vs. 38), and the total tumor load (tumor count, median = 15 vs. 5)." (PMID 39941762, 2025). "Additionally, meningiomas are more commonly observed in NF2 than in Carney complex." (PMID 40713130, 2025). "Additionally, we measured the expression level of EGFR in NF2‐assoicated meningioma cells." (PMID 38828669, 2024). "NF2 gene mutation is associated with the early development of meningiomas and is recognized as the most common gene mutation in cases of atypical meningiomas, present in up to 75% of tumors, making a meningioma 3.78 times more likely to be atypical than without an NF2 gene alteration." (PMID 39202270, 2024). "Notably, mutations of these genes in meningiomas occur to a large degree without concurrent alteration of NF2 or loss of chromosome 22." (PMID 37760490, 2023). "SMO mutations occur in about 5% of meningiomas which do not show alterations in NF2, AKT1 and KLF1." (PMID 36181606, 2023). "Although from a surgical perspective, NF2 mutant meningiomas may be regarded as “simpler” as they tend to originate in more surgically accessible locations, such as the convexity, they are the biologically more aggressive tumors and more likely to become atypical and malignant." (PMID 37010677, 2023). "Type B meningiomas included non-aggressive tumors primarily distinguished by NF2 loss." (PMID 36937440, 2023).
meningioma (continued). "Gene expression-based clustering analyses of YAP1 point mutations have revealed that YAP1 fusion meningiomas resemble low-grade NF2 mutant meningiomas based on the up-regulated genes, whereas, based on the down-regulated genes, YAP1 fusion meningiomas cluster with high-grade NF2 mutant meningiomas." (PMID 37628996, 2023). "Nearly all MG1 meningiomas had NF2 mutations whereas almost no MG2 meningiomas had this alteration." (PMID 36840836, 2023). "Similarly, proliferative meningiomas with NF2 loss but no chromosomal instability demonstrate lower methylated status when compared to other molecular groups." (PMID 36937440, 2023). "Similarly, individuals without the condition can develop sporadic meningioma that contain a NF2 mutation – this is described as NF2 mutated meningioma." (PMID 37860270, 2023). "In addition, 1–5% of meningiomas without alterations in NF2 and AKT1, harbor mutations in the SMO gene, which encodes smoothened homolog, a member of the Hedgehog signaling pathway." (PMID 35565385, 2022). "Additionally, deletion of PTPRJ promotes NF2-dependent meningioma development." (PMID 36611803, 2022). "Given that 40% of meningiomas do not have mutations in NF2, more recent investigation has focused on identifying other drivers of meningioma tumorigenesis using next-generation sequencing techniques that facilitate genome-wide sequencing in large cohorts of patients." (PMID 35402234, 2022). "Interestingly, we found that three patients with NF2 alteration/22q loss (3/7: 42.9%) experienced recurrence even after GTR was achieved, suggesting that sphenoid wing meningiomas with NF2 alteration/22q loss require close postoperative follow-up even if GTR is achieved." (PMID 35804955, 2022). "Irrespective of the histological grade, most meningiomas (55%) exhibit NF2 alterations, while NF2 wild-type meningiomas may harbor mutations in TRAF7, KLF4, PIK3CA or SMO." (PMID 35049691, 2022). "This may be in part because the AKT1 and PiK3CA mutations are rare, found only in 9% and 7% of WHO grade 1 meningiomas without NF2 abnormalities." (PMID 36139608, 2022). "Notably, the PIK3CA-mutant meningiomas lacking mutations in NF2, AKT1, and SMO, tend to express TRAF7 mutations." (PMID 35565385, 2022). "She underwent tumor embolization followed by subtotal resection via expanded endoscopic endonasal approach, with histopathological analysis now consistent with WHO grade 2 meningioma with rhabdoid features and NF2 mutation (genomic sequencing was not available at the time of prior resections)." (PMID 35402234, 2022). "NF2-mutated grade I tumors have a higher density of M2 macrophage infiltration than that of tumors with AKT1 activating mutations, suggesting that this genetic subset of grade I meningiomas may drive immunosuppression." (PMID 35712492, 2022). "Thus, investigating the expression and activation of OGN, mTOR, and NF2 signaling in meningioma cells will not only uncover key molecular mechanisms, but may also provide promising targets for the treatment of meningioma." (PMID 33622177, 2021). "Patients may not benefit from these biomarkers targeting postradiation NF2 gene fusions as these NF2 genes do not predict the risk of recurrence in the initial diagnosis of meningioma." (PMID 33807688, 2021). "NF2 null mice die during embryonic development due to a failure to initiate gastrulation, while heterozygous models resulted in widespread tumor development, and conditional NF2 gene inactivation in leptomeningeal cells resulted in the development of meningiomas." (PMID 33262459, 2021). "In addition, NF2 patients often develop multiple meningiomas and ependymomas at an early age." (PMID 34072574, 2021).
meningioma (continued). "It is postulated that craniospinal radiation may also lead to NF2 intronic rearrangements/fusion events (found in 39% RIM vs 0% sporadic meningioma) as opposed to mutations seen in sporadic meningioma, subsequently leading to inactivation." (PMID 33886110, 2021). "The genomic landscape of meningiomas can be broadly classified into two subsets that focus on the involvement of the Neurofibromatosis type 2 (NF-2) gene—tumors associated with mutations of NF-2 and tumors with non-NF-2 mutations." (PMID 34638590, 2021). "Interestingly, none of the other meningioma subtypes with characteristic alterations, e.g. mutations in NF2, TRAF7/KLF4 or BAP1, or YAP1 fusion, seem to form epigenetic clusters that are distinct to the same extent." (PMID 33319313, 2021). "Progressive meningiomas harboring this mutation have been categorized in the NF2-exclusive pattern, that lacks NF2 mutation and associates with skull base localization and female sex, similarly to the two AKT1-mutated atypical meningiomas identified in this study." (PMID 33670055, 2021). "Furthermore, patients with sporadic VS or meningiomas may also be considered as a surrogate model for NF2 patients." (PMID 33604573, 2021). "However, a recent study compared the molecular profiling of cranial and spinal meningiomas in NF2." (PMID 33445724, 2021). "Thus, this group can be described as the NF2-driven subgroup of pediatric meningiomas." (PMID 34495383, 2021). "Approximately half of sporadic meningiomas of all grades are found to harbor NF2 mutations with an overwhelming majority having either complete or partial loss of heterozygosity on chromosome 22q leading to a nonfunctional neurofibromin-2." (PMID 33346248, 2020). "Furthermore, we found that the tumor suppressor gene and chromatin regulator KDM6A, which has been identified at low frequency in prior studies with smaller cohorts of meningioma, is more frequently altered in NF2-mutant high-grade meningiomas than previously noted." (PMID 33087175, 2020). "Therefore, it is not surprising that NF2-mutated meningiomas have been found to harbor more genetic alterations than the NF2-wildtype, despite both meningiomas within the same benign grade, which has continued the suggestion that a NF2 mutation results in greater chromosomal instability overall." (PMID 33194703, 2020). "Interestingly, following serial passaging, NF2-deficient but not NF2-expressing meningioma cultures developed foci with aggressive phenotype, manifested by anchorage independence and rapid cell proliferation." (PMID 31963394, 2020). "In addition, nearly 10% of non-NF2 meningiomas harbor loss of function mutations of KDM5C and KDM6A, encoding histone lysine-specific demethylases, resulting in alterations in histone function and epigenetic regulation in meningiomas." (PMID 33194703, 2020). "Similarly, sporadic meningiomas with NF2 inactivation also tend to be of the fibrous subtype." (PMID 31161239, 2020). "Taking into account that KDM6A, which is located on chromosome X and escapes X-inactivation, acts antagonistically to PRC2 and promotes H3K27 demethylation, our findings may partly explain the upregulated PRC2 activity in the NF2-mutant group of meningiomas after inactivation of KDM6A." (PMID 33087175, 2020). "Moreover, over-expression of an oncogenic allele of the Hedgehog pathway activator Smoothened (SMO) promotes arachnoid hyperproliferation in mice, but does not cause meningiomas of the same size or number as inactivating alleles of Nf2." (PMID 32690089, 2020).
meningioma (continued). "However, the early recognition of the crucial role of NF2 mutations in the pathogenesis of the majority of meningiomas has not yet translated into useful clinical insights, due to the complexity of merlin’s many interacting partners and signaling pathways." (PMID 31652973, 2019). "Interestingly, this cytogenetic profiles seems to be independent of NF2 mutation, as well as other common driver mutations identified in grade I meningioma." (PMID 31970090, 2019). "Moreover, the findings also suggest that NF2-driven meningiomas may exhibit a more indolent course than non-NF2-driven meningiomas." (PMID 31191822, 2019). "Patients with NF2 mutant meningiomas were on average 10 years older than patients without an NF2 mutation, suggesting that NF2-driven meningiomas may display a slower growing, more indolent disease course." (PMID 31191822, 2019). "Interestingly, recurrent mutation in PRKAR1A has been reported in few meningioma cases with non-mutated NF2 gene." (PMID 31671850, 2019). "However, only knockdown of KIF11 resulted in a markedly reduced tumor cell proliferation in Ben-Men-1 cells and the newly established anaplastic NF2-mutated meningioma cell line NCH93, proposing KIF11 as a novel prognostic marker and therapeutic target." (PMID 30991738, 2019). "Nevertheless, there has been no single study examining the relationship between the expression of PR and NF2 in the pathogenesis of meningioma by showing direct evidence of the inter-relationships between the use of exogenous progesterone, expression of PR, NF2. and meningioma." (PMID 30687635, 2018). "We proposed that NF2 inactivation might have distinct role in the complex pathogenesis of meningioma, which filled the gap between the use of exogenous progesterone and the development of meningioma in females." (PMID 30687635, 2018). "Besides the association of -22q with the impairment of NF2 function, impact of other chromosome arm losses are not thoroughly understood in the molecular etiology of meningiomas." (PMID 27096627, 2016). "In addition to the CDKN2A/CDKN2B genes, the KLF4 (Kruppel like factor 4) gene has also been recently reported to be mutated in meningiomas (particularly among secretory tumors) in association with lack of NF2 mutation." (PMID 25965831, 2015). "Most interestingly, such mutations were shown to correlate with specific clinico-histopathological characteristics (e.g. tumor localization and histopathological subgroups) as well as with a subset of meningiomas lacking NF2 mutation, bringing new insight into NF2 non-mutated tumors." (PMID 25965831, 2015). "Notably, whereas both NF2−/− meningioma cell lines (Ben-Men and KT21) were highly sensitive to PF3758309, with IC50 values in the low to mid nM range, NF2-expressing meningioma cells showed much less sensitivity to this compound (IC50 3.4 μM and 5.3 μM for MN328 and MN525 cells, respectively)." (PMID 25596744, 2015). "Thus, while Paks are required for Erk activation in many cell types, this does not appear to be the case in the setting of NF2-deficient schwannomas or meningiomas." (PMID 25596744, 2015). "Monosomy 22 in association or not with mutation of the NF2 gene, is by far the most frequent chromosomal alteration in meningiomas although other genes in this chromosome, as well as other chromosomes have also been found to be recurrent altered in these tumors." (PMID 25965831, 2015). "Interestingly, recent reports have identified SMO mutations in meningiomas lacking NF2 mutations, which further supports the potentially relevant role of this pathway in the development of at least some meningiomas." (PMID 25965831, 2015). "We further show that the selective mTOR kinase inhibitor AZD2014, targeting both mTORC1 and mTORC2, is more efficient than rapamycin in blocking proliferation of primary human meningioma cells and thus may hold promise as a more effective therapeutic option for NF2 patients." (PMID 26219339, 2015).